CUL1 (cullin 1)
Diseases named in the same sentence as CUL1 in open-access papers (continued):
Sharing a sentence is not in itself a finding about the gene and the disease.
infection (11 papers, 2010 to 2025). The state of being infected such as from the introduction of a foreign agent such as serum, vaccine, antigenic substance or organism. "The results above have demonstrated that BY-RFP infection and knockdown of LsCSN5 inhibited de-neddylation process of CUL1, which would cause defective SCF E3 ligase complexes." (PMID 37717061, 2023). "For example, the Sendai virus (SeV) upon infection causes NEDDylation-dependent proteasomal degradation of IRF3 by utilizing Cul1 (Cullin-1) based ubiquitin ligases." (PMID 33396899, 2020). "Western-blotted nuclear and cytoplasmic fractions of uninfected and O. tsutsugamushi infected cells were examined 72 h post infection (hpi) with Cul1, Skp1, and Rbx1 antibodies." (PMID 39976440, 2025). "Cross-referencing a published list of 2,704 Cul1 target genes with our RNAseq analysis of O. tsutsugamushi-infected HeLa cells identified 107 Cul1 target genes that are upregulated during infection (Data Set S1)." (PMID 39976440, 2025). "Firstly, we examined accumulation of LsCUL1 in healthy or BY-RFP-infected SBPHs, and showed that BY-RFP infection led to significantly increased ratio of CUL1Nedd (CUL1 with Nedd8 moiety) to CUL1, indicating that BY-RFP interfered with de-neddylation of CUL1." (PMID 37717061, 2023). "Following infection, the levels of neddylated forms of CUL1, 2, 3, 4A and 4B increased in presence of the wild-type Cif proteins from E. coli or from B. pseudomallei." (PMID 20941356, 2010). "To further examine this hypothesis, we depleted endogenous Cullin 1 or β-TRCP via lentiviral shRNA infection to examine its effects on MTSS1 abundance." (PMID 24318128, 2013). "CUL1 and CCNE1, two S phase target genes, whose mRNA levels were upregulated at various time points after DTMUV infection, while the mRNA levels of RBX1, SKP2 and CCNE2 were decreased at all the time points, moreover, CCNE2 was time-dependently downregulated." (PMID 32897243, 2020). "Significant reductions in nuclear Cul1 levels were also observed at 24 hpi in HeLa cells inoculated with different multiplicities of infection (MOI) but not in infected HeLa cells that had been treated with the bacterial translation inhibitor, chloramphenicol." (PMID 39976440, 2025). "HeLa-CD4 cells were transfected twice (24 h apart) with either a non-targeting siRNA or siRNA targeting cullin 1, followed by infection with either DHIV-GFP WARO (Vpu+/Nef−) or DHIV-GFP (Vpu−/Nef−)." (PMID 26215564, 2015). "Although the overexpression of dominant negative Cullin-1 (DN-CUL1) led to an upregulation of MCL1 in non-infected cells, infection with JEV still suppressed MCL1 expression." (PMID 30261081, 2018). "Next we examined the effects of knocking down SKP1, CUL1, FBXW11 alone or in combination, in the presence or absence of PKR, on infection levels of RVFV ZH501 in HeLa cells." (PMID 26837067, 2016).
CUL1 also shares sentences with these, for which no sentence is quoted: glioma (3 papers); non-small cell lung carcinoma (2); basal cell carcinoma (1); depression (1); dysplastic nevi (1); HCMV infection (1); HIV-1 infection (1); inflammatory bowel disease (1); intestinal cancer (1); intrauterine growth retardation (1); malignant brain tumors (1); myocardial ischemia (1); neurodegenerative disease (1); oral cancer (1); overnutrition (1); pregnancy disease (1); Rb (1); serous ovarian cancer (1); spontaneous abortion (1).